CXCL13 (C-X-C motif chemokine ligand 13)
Description:
Chemotactic for B-lymphocytes but not for T-lymphocytes, monocytes and neutrophils. Does not induce calcium release in B-lymphocytes. Binds to BLR1/CXCR5.
Synonyms: BCA-1; BCA1; BLC; SCYB13; BLR1L; ANGIE; ANGIE2
Tractability: Antibody: its Gene Ontology location is reachable by antibodies, with high confidence; UniProt places it where antibodies can reach, with medium confidence; UniProt predicts a signal peptide or a membrane-spanning region. PROTAC: ubiquitination databases record sites on it.
Gene: Protein-coding gene on chromosome 4 (77,511,753 to 77,611,834, forward strand). Ensembl gene ENSG00000156234.
Subcellular location: Secreted
Pathways (Reactome):
Signal Transduction: Chemokine receptors bind chemokines; G alpha (i) signalling events
Gene Ontology:
Molecular function: CCR10 chemokine receptor binding; chemokine activity; CXCR3 chemokine receptor binding; CXCR5 chemokine receptor binding; fibroblast growth factor binding; heparin binding; receptor ligand activity; CXCR chemokine receptor binding
Biological process: B cell chemotaxis; cell surface receptor signaling pathway; cell-cell signaling; defense response to bacterium; endothelial cell chemotaxis to fibroblast growth factor; negative regulation of endothelial cell chemotaxis to fibroblast growth factor; positive regulation of cytosolic calcium ion concentration; positive regulation of T cell chemotaxis; antimicrobial humoral immune response mediated by antimicrobial peptide; cellular response to lipopolysaccharide; chemokine-mediated signaling pathway; chronic inflammatory response; germinal center formation; immune response; inflammatory response; lymphocyte chemotaxis across high endothelial venule; neutrophil chemotaxis; positive regulation of cell-cell adhesion mediated by integrin; positive regulation of integrin activation; regulation of angiogenesis; regulation of humoral immune response; regulation of Rap protein signal transduction; chemotaxis; defense response
Cellular component: extracellular region
Genetic constraint (gnomAD): Loss-of-function variants: 1 observed, 6.1 expected, observed/expected ratio (o/e) 0.16, 90% interval 0.057 to 0.78. That is too few expected variants to judge how well the gene tolerates losing a copy. Missense variants: 41 observed, 58.8 expected, observed/expected ratio (o/e) 0.7, 90% interval 0.54 to 0.9. Synonymous variants: 12 observed, 18.36 expected, observed/expected ratio (o/e) 0.65, 90% interval 0.42 to 1.06.
Homologues: Orthologues: chimpanzee CXCL13 (99% identical), macaque CXCL13 (92% identical), dog CXCL13 (56% identical), rabbit CXCL13 (56% identical), mouse Cxcl13 (46% identical), rat Cxcl13 (44% identical). Paralogues in human: CXCL8 (28% identical), CXCL10 (26% identical), CXCL2 (25% identical), CXCL6 (25% identical), PPBP (25% identical), CXCL3 (24% identical), CXCL1 (23% identical), CXCL5 (23% identical), CXCL9 (23% identical), PF4V1 (23% identical), PF4 (22% identical), CXCL11 (19% identical).
Diseases named in the same sentence as CXCL13 in open-access papers:
CXCL13 is named in the same sentence as 436 diseases in open-access papers, as found by Europe PMC text mining. Sharing a sentence is not in itself a finding about the gene and the disease. The quoted sentences say what the papers report.
breast cancer (125 papers, 2008 to 2026). A primary or metastatic malignant neoplasm involving the breast. "Previous studies have shown that CXCL13 is associated with the prognosis of various cancers including oral squamous cell carcinoma and breast cancer." (PMID 36639648, 2023). "CXCL13 expression at high levels corresponds with T cells expansion after anti-PD-1 treatment for breast cancer, which is associated with a good response to immunotherapy." (PMID 35053457, 2022). "High levels of Ccl17, Cxcl13, and Cxcr3 in mammary tumors or tumor-associated macrophages induce cancer cell migration which is associated with metastasis disease." (PMID 35768767, 2022). "In this study, The Cancer Genome Atlas database analysis revealed that CXCL13 was overexpressed in various human cancers including breast carcinoma, and associated with good clinical prognosis in breast cancer." (PMID 35693216, 2021). "Improved prognosis in human breast cancer is associated with CD4+ Tfh cells which produce an abundance of Cxcl13 and support B cell differentiation, TLS formation and GC maturation." (PMID 34122434, 2021). "For instance, in human breast cancer tumor tissues greater CXCL13 expression was linked with increased T cell and B cell tumor recruitment." (PMID 33193299, 2020). "We report here, to our knowledge for the first time, based on a large study that the humoral immune function, as approximated with cancer B cell-attracting chemokine CXCL13 content, is associated with survival in early breast cancer." (PMID 29482642, 2018). "The presence of CXCL13+ T cells in breast cancer tissue was found to be a good prognostic sign, associated with a higher rate of disease-free survival." (PMID 30190721, 2018). "The increasing expression of CXCL13 observed in several human tumors (including breast cancer, colon cancer and PCa) has been implicated in cancer progression by inducing cell migration and invasion." (PMID 28881808, 2017). "Indeed, we found that the association strength can differ by breast cancer subtype, although we only observed a statistically significant difference in the association signals for CXCL13 with interval cancer vs. screen-detected cancer." (PMID 38135714, 2024). "In our results, CXCL13 was a protective factor in breast cancer and a risk factor in lung cancer." (PMID 38075694, 2023). "It was found that a high serum level of CXCL13 protein is a potential good prognosis indicator for hepatocellular carcinoma, but it was also found to be associated with a poor prognosis in patients with prostate cancer and breast cancer." (PMID 36467500, 2022). "For clear cell renal cell carcinoma, gastric cancer, breast cancer and hepatocellular carcinoma, CXCL13 had good diagnostic and prognostic value, hence may become a candidate biomarker and therapeutic target." (PMID 34621670, 2021). "However, a large number of studies have demonstrated that the CXCL13/CXCR5 axis is closely associated with breast cancer growth and lymph node metastasis." (PMID 34947813, 2021). "Likewise, the recent association between high CXCL13 and distant disease-free survival in early-stage breast cancer patients provided evidence that humoral immunity influences the survival outcomes in these patients, particularly those with TNBC." (PMID 31354634, 2019). "High tumor CXCL13 expression was associated with several factors that are generally associated with poor survival in breast cancer, such as low cancer histological grade of differentiation, high Ki-67 expression, and negative ER expression in the FinHer trial patient population." (PMID 29482642, 2018). "Furthermore, the validations with clinical samples and correlation analysis demonstrated that CXCL13 was indeed highly expressed in young breast cancer and closely associated with some prognostic factors including lymph node positive and ER negative." (PMID 25990390, 2015).
breast cancer (continued). "This may be helpful for establishing a potential association between CXCL13 and young breast cancer, explaining why young patients with breast cancer are prone to develop metastasis and why young age at diagnosis are associated with poor prognosis." (PMID 25990390, 2015). "Therefore, our data suggest that CXCL13 may be an unidentified gene associated with young breast cancer and deserves further investigation." (PMID 25990390, 2015). "In breast cancer, CXCL13 density positively correlates with disease-free survival and response to chemotherapy." (PMID 40352278, 2025). "For example, the expression of CXCL13 in the microenvironment of mouse breast cancer can regulate the infiltration of immune cells to induce anti-tumor immune responses." (PMID 39980564, 2025). "Intriguingly, single-cell data from breast cancer patients undergoing ICB revealed that both CD4+CXCL13+ and CD8+CXCL13+ T cell populations possess predictive value for ICB treatment response." (PMID 40883281, 2025). "High expression of CXCL13 and CXCR5 in breast cancer tissues was found to be associated with increasing stage, lymph node metastasis, distant metastasis, and disease stage, but not with HER2 status, histological type, or tumor size." (PMID 39001456, 2024). "As a member of the inflammatory chemokine family, inhibition of CXCL13 has been shown to promote apoptosis and suppress proliferation of breast cancer cells." (PMID 39834939, 2024). "For example, CXCL13 has a protective prognostic action (p < 0.05, HR < 0) in breast cancer and skin melanoma." (PMID 39064019, 2024). "The apoptotic pathway and CXCL13 have been reported only in a few diseases such as breast cancer, lung adenocarcinoma, and cerebrovascular disease." (PMID 38459390, 2024). "The high expression of CXCL13 and CXCR5 in breast cancer tissue was found to be associated with lymph node metastasis, distant metastasis, and a more advanced disease stage." (PMID 39001456, 2024). "In breast cancer, miR-186-5p was corrected with tumour size and tumour staging by downregulating CXCL13." (PMID 38012562, 2023). "In recent years, several studies have reported the involvement of CXCL13 in the progression, metastasis, prognosis, apoptosis, and adaptive immunity of tumors, including breast cancer." (PMID 37958571, 2023). "In breast cancer (where high levels of CXCL13 expression are an independent prognostic factor) CD4+ T cells are the dominant intratumoral source of CXCL13 and correlate with increased B cell infiltration and maturation." (PMID 37520560, 2023). "Cochrane’s Q test did not provide evidence of heterogeneity between CCL1 (p = 0.227), CCL2 (p = 0.982), CCL18 (p = 0.221), CXCL5 (p = 0.533), CXCL12 (p = 0.977), and CXCL13 (p = 0.520) and breast cancer." (PMID 38075694, 2023). "When a CXCL13-coupled CpG ODN was applied in mice with 4T1 breast cancer metastasis, it successfully stimulated effector TIL-B cells via the CXCL13-CXC5R interaction, promoted GrB-expressing CTLs, without stimulating the CD20low Breg cells." (PMID 37868967, 2023). "Whereas in both breast cancer and nasopharyngeal carcinoma, CXCL13-producing CD4+ T cells with either PD-1hiT-bethiBCL6lowCXCR5- or PD-1hiCXCR5- phenotype prime TLS neogenesis." (PMID 37868967, 2023). "In RCB II/III breast cancer, patients with high expression of EV_APRIL (67.4% vs. 84.0%; p = 0.049), EV_CXCL13 (67.2% vs. 89.5%; p = 0.015), and EV_VEGF-A (66.0% vs. 87.0%; p = 0.020) had shorter OS than those with low cytokine expressions." (PMID 37958571, 2023). "There are rare studies that evaluate the value of CXCL13 as a blood-based biomarker in breast cancer." (PMID 37958571, 2023). "For instance, CXCL13 elevation was related to a poor prognosis in breast cancer, and CCR7 upregulation in some cancer cells enhanced lymph node metastasis." (PMID 36890557, 2023).
breast cancer (continued). "A recent study showed that breast cancer cells expressing CCL21 induced CXCL13 secretion from stromal cells through the recruitment of innate lymphoid cells to the tumor microenvironment." (PMID 37958571, 2023). "The increased level of CXCL13/CXCR5 coarticulation in ER (+) breast cancer cells with lower Nrf2 levels helps advance tumor intrusion and metastasis." (PMID 35571115, 2022). "The CXCL13-producing CD4+ T cells reported in breast cancer and nasopharyngeal cancer had similar characteristics." (PMID 35552285, 2022). "The authors also analyzed a cohort of 996 patients with breast cancer who received neoadjuvant chemotherapy, which showed that CXCL13 expression was highly correlated with a complete response in HER2+ patients." (PMID 35053457, 2022). "We also identified CXCL13 as another early factor correlating with 4T1 tumour growth, and its role in breast cancer has been widely reported." (PMID 35226704, 2022). "BMP4 and C3 were significantly expressed in normal tissue as compared to cancerous breast cancer tissues whereas CXCL13 and DKK1 is observed to be expressed in breast cancer tissue as compared to normal breast tissue." (PMID 34754042, 2021). "Pparγ1+/+ ErbB2 mammary tumors showed increased expression of specific chemokines and cytokines (Cxcl5, Cxcl19, Cxcl13, IL1b and Tnfrsf13c)." (PMID 33946495, 2021). "Flow cytometry detection also found upregulated intracellular CXCL13 expression in human breast cancer cell lines." (PMID 35693216, 2021). "In breast cancer cells, the decrease in CXCL13 leads to the decreased expression of CXCR5, p-ERK/ERK, and cyclin D1 as well as the increased expression of cleaved Casp-9, which is an initiator caspase protease for apoptosis." (PMID 34947813, 2021). "CXCL13 facilitates breast cancer cell line migratory activity via the nuclear factor kappa-B ligand (RANKL)-Src pathway, which mediates the upregulation of EMT regulators and matrix metalloproteinase-9 (MMP9)." (PMID 34947813, 2021). "As expected, parental 4T1 and 4T1-CXCL13 cells showed no obvious CXCR5 expression both in vitro and in vivo, which can probably explain the previously contradictory findings of CXCL13 in breast cancer." (PMID 35693216, 2021). "Breast cancer cell lines undergoing CXCL13 stimulation overexpress EMT regulators and MMP9 via the nuclear factor kappa-B ligand (RANKL)-Src pathway, which is critical for breast cancer cell progression and migration." (PMID 34947813, 2021). "A recent study showed that CXCL13 expression is increased in the sera of breast cancer patients with brain metastases, though the role and mechanism of action of the CXCL13/CXCR5 axis in cancer metastasis remain to be elucidated." (PMID 34947813, 2021). "The CXCL13/CXCR5 axis is related to improved outcomes of human epidermal growth factor receptor 2 (HER2)-positive breast cancer." (PMID 34947813, 2021). "In breast cancer, an anti-CXCL13 antibody suppressed tumor growth by inhibiting the TGF-β1, IL-1, TNF, cyclin D1, and CXCR5/Erk pathways and repressed tumor metastasis by inhibiting RANKL production." (PMID 34947813, 2021). "The characteristics of CD4+CXCL13+ T cells in LR-CHL are very similar to a CXCL13-producing TFH population that lacks CXCR5 expression identified in breast cancer." (PMID 34615710, 2021). "CXCL13 was found to be overexpressed in breast cancer and in the peripheral blood of patients with breast cancer." (PMID 34947813, 2021). "An example of this is drugs which block the CXCL13→CXCR5 axis, with in vitro studies on breast cancer cells showing that anti-CXCL13 antibodies induce tumor cell apoptosis." (PMID 33467722, 2021). "Previous studies have reported contradictory performance of chemokine CXC motif ligand 13 (CXCL13) in breast cancer." (PMID 35693216, 2021). "As a result, breast cancer patients with higher CXCL13 expression showed a significantly longer DFS." (PMID 35693216, 2021).
breast cancer (continued). "Treatment of the endothelial cells that constitute the BBB with the sera of patients with breast cancer selectively increases the expression of CXCL13 and the permeability across the barrier using fluorescein." (PMID 33466236, 2021). "Both a high abundance of Tfh cells and a high expression level of CXCL13 correlated with increased survival in breast cancer and colorectal cancer." (PMID 34220837, 2021). "CX3CL1 and CXCL13 were found to be elevated in the sera of patients with breast cancer brain metastases." (PMID 33466236, 2021). "The results indicated that the expression levels of CXCL9, CXCL10, CXCL11, and CXCL13 were marked higher in breast cancer tissues than in normal tissues, while the expression levels of CXCL1, CXCL2, CXCL3, and CXCL12 were lower inversely." (PMID 32963527, 2020). "Immunohistochemistry was used to detect the expression of CD8, Ki-67, and CXCL-13 in the 89 breast cancer tissues." (PMID 33585256, 2020). "CXCL13 has been reported to contribute to cancer progression in breast cancer by recruiting B lymphocytes into tumor microenvironment." (PMID 32963527, 2020). "Among the chemokines tested, CX3CL1 and CXCL13 were selectively and significantly increased in patients with cerebral metastases of breast cancer." (PMID 32321535, 2020). "The abundance of lymphoid chemokines such as CXCR5 and CXCL13 has been linked to both the presence of TLS and HEV in breast cancer stroma." (PMID 32605588, 2020). "In breast cancer cell lines, CXCL13 induced changes of epithelial-to-mesenchymal transition marker expression." (PMID 32321535, 2020). "The addition of CXCL13 to breast cancer cells in vitro increased expression of matrix metalloproteinase-9 (MMP-9) and genes reasonable for driving the epithelial to mesenchymal transition (EMT)." (PMID 33193299, 2020). "In an early study using CXCR5-expressing breast cancer cells, CXCL13 induced changes in the expression of markers consistent with epithelial-to-mesenchymal transition (EMT)." (PMID 31354634, 2019). "Perturbation of plasma levels of CXCL-13 is associated with activation of the host's immune response, and CXCL-13 is used as an indicator of breast cancer, cutaneous vasculitis, and various lupus-like condition and bacterial infections." (PMID 31886231, 2019). "Extra backing proof of the concept that CXCL13 plays a pivotal role in breast cancer growth and lymph node metastasis was gained in tumorigenesis experiments using 4T1 breast cancer cells." (PMID 31354634, 2019). "Using a microarray analysis, a study found significant CXCL13 overexpression in breast cancer specimens." (PMID 31354634, 2019). "The analysis of a T-cell signature in breast cancer that includes CXCL13 revealed additional levels of complexity." (PMID 31354634, 2019). "In univariate analysis, mRNA expression of CXCL13 and other T-cell markers associate with longer metastasis free-survival, with a stronger prognostic effect in HER2 positive breast cancer." (PMID 31354634, 2019). "Breast cancer exhibits one of the strongest relationships between CXCL13:CXCR5 axis and tumor progression." (PMID 31354634, 2019). "In breast cancer tissue, CXCL13+ CD4+ T cells accumulate either within small B cell aggregates, adjacent to B cell follicles, or occasionally within B cell follicles." (PMID 30190721, 2018). "CXCL13 has been reported to be involved in several cancer types, including prostate cancer, breast cancer, colorectal cancer, and lung cancer." (PMID 30723697, 2018). "Serum level of CXCL13 is increased in metastatic breast cancer patients compared with normal donor and postoperative breast cancer patients." (PMID 30723697, 2018). "While most CXCL13+ T cells in breast cancer samples are CD4+ T cells, a subset of tumor-infiltrating CD8+ T cells was also noted to produce CXCL13 and reside near B cell follicles, albeit with lower CXCL13 expression than in CD4+ T cells." (PMID 30190721, 2018).